CATSPERZ (catsper channel auxiliary subunit zeta)
Description:
Auxiliary component of the CatSper complex, a complex involved in sperm cell hyperactivation. Sperm cell hyperactivation is needed for sperm motility which is essential late in the preparation of sperm for fertilization. Required for a distribution of the CatSper complex in linear quadrilateral nanodomains along the flagellum, maximizing fertilization inside the mammalian female reproductive tract. Together with EFCAB9, associates with the CatSper channel pore and is required for the two-row structure of each single CatSper channel.
Synonyms: C11orf20; TEX40; DKFZP566E164
Tractability: Antibody: UniProt places it where antibodies can reach, with high confidence; its Gene Ontology location is reachable by antibodies, with medium confidence. PROTAC: ubiquitination databases record sites on it.
Gene: Protein-coding gene on chromosome 11 (64,300,358 to 64,304,770, forward strand). Ensembl gene ENSG00000219435.
Subcellular location: Cell projection, cilium, flagellum membrane
Subcellular location (Human Protein Atlas): Mid piece; Primary cilium tip; Cytosol; Principal piece
Gene Ontology:
Biological process: flagellated sperm motility; male meiotic nuclear division; sperm capacitation; spermatogenesis
Cellular component: cytoplasm; sperm midpiece; sperm principal piece; CatSper complex
Genetic constraint (gnomAD): Loss-of-function variants: 21 observed, 18.53 expected, observed/expected ratio (o/e) 1.13, 90% interval 0.8 to 1.62. The synonymous counts are far from expectation, so gnomAD's model fits this gene poorly and the ratio says little. Missense variants: 234 observed, 207.12 expected, observed/expected ratio (o/e) 1.13, 90% interval 1.01 to 1.26. Synonymous variants: 127 observed, 85.21 expected, observed/expected ratio (o/e) 1.49, 90% interval 1.29 to 1.73.
Homologues: Orthologues: macaque CATSPERZ (94% identical), dog CATSPERZ (56% identical), mouse Catsperz (47% identical).
Diseases named in the same sentence as CATSPERZ in open-access papers:
CATSPERZ is named in the same sentence as 8 diseases in open-access papers, as found by Europe PMC text mining. Sharing a sentence is not in itself a finding about the gene and the disease. The quoted sentences say what the papers report.
infertile (2 papers, 2017 to 2022). "An intriguing aspect of our observations is that, unlike CatSper1-4 and d-null mice, which produce complete infertility, CatSperz-null males exhibit an incomplete loss of fertility." (PMID 28226241, 2017).
CATSPERZ also shares sentences with these, for which no sentence is quoted: Serous Ovarian Carcinoma (3 papers); cancer (2); acute promyelocytic leukemia (1); extraskeletal myxoid chondrosarcoma (1); melanoma (1); ovarian carcinoma (1); Tumor (1).